RHOA (ras homolog family member A)
Diseases named in the same sentence as RHOA in open-access papers (continued):
Sharing a sentence is not in itself a finding about the gene and the disease.
tumor (continued). "In gastric cancer, transforming growth factor β (TGFβ) induces RhoA activation and RLC phosphorylation, increasing tumor migration speed and invasiveness." (PMID 26542704, 2015). "Both HNF4α and miR-122 act as tumor suppressors and negative regulators of HCC invasion and metastasis, whereas RhoA positively regulates HCC invasion and metastasis." (PMID 24992599, 2014). "PAK1 and PAK2 have been shown to differentially modulate adhesion, RhoA activity and MLC phosphorylation during mast cell degranulation and tumor cell migration." (PMID 24019894, 2013). "Fluvastatin inhibited the activation of the small guanosin triphosphate binding protein (GTP) RhoA and the consequent actin redistribution induced by ligation of LFA1 involved in NK-tumor target cell adhesion." (PMID 23667543, 2013). "A similar role of the RhoA/ROCK cascade has been established in fibroblast and in other tumor cells, where it mediates ezrin activation or redistribution." (PMID 21818323, 2011). "Since in 2D tumor cell motility is strongly dependent on the expression and functioning of integrins, FAK and RhoA, these proteins were analyzed in 3D after drug treatment." (PMID 20707917, 2010). "Further to our data demonstrating that LPA drives tumour cell invasion through both NET1 and RhoA, we next investigated the role of the cytoskeleton in these processes." (PMID 18827818, 2008). "Additionally, CAFs contribute to ECM restructuring through the enzymatic activity of MMPs and the RhoA–ROCK pathway, thereby generating physical conduits that facilitate tumor cell motility, invasiveness, and resistance to therapeutic agents." (PMID 41583435, 2025). "Additionally, hyperactivate RhoA signaling is both necessary and sufficient to drive oncogenic TEAD/YAP transcription in tumor." (PMID 40845099, 2025). "The presence of bacteria within tumor cells has been shown to suppress the RhoA/ROCK signaling pathway, thereby facilitating the adaptation of circulating tumor cells to fluid shear stress through cytoskeletal remodeling and enhancing their potential for distant colonization." (PMID 41514613, 2025). "These antibodies can induce NK cell infiltration into tumors by binding to CXCL16, while simultaneously activating Ras Homolog Family Member A (RhoA) through the extracellular signal-regulated kinase (ERK) signaling cascade, further boosting NK cell-mediated tumor targeting." (PMID 39859231, 2025). "Moreover, through signaling pathways such as Nrf2, RhoA/ROCK, EGFR/PI3K/Akt, Bax, and PI3K/Akt/mTOR, BJ also suppresses tumor proliferation and metastasis." (PMID 41156537, 2025). "RhoA/ROCK1 signaling-activated actin contractility promotes the conversion of fibroblasts to CAFs, which in turn leads to physical remodeling of the pro-invasive ECM, favoring tumor aggressiveness and dissemination." (PMID 40655948, 2025). "RHOA lactylation at K118 (activation) and K162 (stabilization) orchestrated by the PCAF/HDAC3 enzymatic axis, enables constitutive oncogenic signaling to fuel tumor progression." (PMID 41291745, 2025). "This suggests that inducing tumor vascularization may act through a signaling pathway composed of ECT2, RhoA, RhoA-GTP, ERK, and VEGF/MMP." (PMID 40655948, 2025). "It has been shown that RACK1 is closely related to tumor progression due to its modulation of multiple signaling pathways including PKC, receptor tyrosine kinase/PI3K/AKT, ERK/MAPK, STAT3, Src/FAK, NF-κB, Wnt/β-catenin, and RhoA/Rho pathway." (PMID 38398158, 2024).
tumor (continued). "The hypoxic CRC cell‐derived exosome circ‐133 is able to translocate to normal tumor cells and promote migration via the miR‐133a/guanine nucleotide exchange factor‐H1 (GEF‐H1)/RhoA axis, suggesting a difference in metastatic potential between hypoxic and relatively normoxic cancer cells." (PMID 39239069, 2024). "Indeed, this circRNA is involved in the sponging of miR-122 and ZO-1, a tight junction protein, as well as in the overexpression of RhoA and RhoA-GTP, crucial genes for tumor invasion and metastasis." (PMID 38672229, 2024). "Overexpression of a constitutively active (CA) mutant of RhoA in GBM TICs restores their mechanosensitivity to ECM stiffness, retards cell motility on soft ECMs by increasing myosin-dependent cell contractility, and suppresses tumor invasion in vivo." (PMID 37864030, 2023). "Aberrant expression of VM production-related proteins (MMP2, MMP9, VEGFA, Laminin, Wnt3a, RHOA) as well as immune checkpoint (PD-L1) in tumors and the occurrence of EMT process are considered to be important drivers of VM formation and tumor development as well as metastasis." (PMID 37407689, 2023). "IGF/IGF-1R mediates cell survival and induces tumor cell invasion and metastasis by crosstalk with the STAT3 signaling pathway, thereby enhancing tumor cell invasion and metastasis, and IGF/IGF-1R can induce cell migration through the PKD or RhoA/PKC signaling pathway." (PMID 36698167, 2023). "In turn, EGFR, IGF1 and MAPK1 mRNA expression levels were significantly decreased, while RHOA mRNA expression was not significantly downregulated in tumor tissues." (PMID 36882618, 2023). "These neoplasms feature a characteristic and similar, but not identical, mutational landscape with mutations in epigenetic modifiers (TET2, DNMT3A, IDH2), RHOA, and T-cell receptor signaling genes." (PMID 36793612, 2023). "We focused on the RhoA mechanism since this protein is commonly activated by multiple Gα proteins and promotes cell migration and invasiveness, and identified that the function of NPFFR2 on tumor progression depends on the RhoA pathway." (PMID 36497331, 2022). "Several studies have demonstrated that CXCR4 could promote cell proliferation in pulmonary vasculature and some tumor cells via PI3K/Akt and RhoA/ROCK signaling pathway." (PMID 35865003, 2022). "Therefore, we concluded that LEMD1 affected cytoskeletal changes by activating the RhoA/ROCK signaling pathway, thus promoting EMT and tumor metastasis." (PMID 35619906, 2022). "Reduced expression of RhoA impairs vGPCR-induced VEGF expression and secretion, cell survival and proliferation, and transformation both in cell culture and in a murine allograft tumor model." (PMID 36212441, 2022). "The expression levels of RHOA, SATB2, and WAVE3 were all downregulated after 48 hours of GBK treatment, indicating that the tumor suppression effect exerted by GBK may be related to invasion/metastasis-associated signaling pathways." (PMID 36313626, 2022). "The tumor activated the RhoA/ROCK signaling pathway but not downstream phosphorylation, ET or the NO system." (PMID 35811723, 2022). "Importantly, tumor invasion-related proteins and pathways represented by RAC, FAK, CDC42, and RhoA signaling were enriched only in the DM group, demonstrating unique characteristics of metastatic CRC." (PMID 35589723, 2022). "Circ-IRAS enters microvascular endothelial HUVECs via exosomes from PC cells, downregulates miRNA-122 and ZO-1, upregulates RhoA and RhoA-GTP, increases F-actin expression and focal adhesion, increases the permeability of endothelial monolayer, and promotes tumor invasion and metastasis." (PMID 35382838, 2022). "Interestingly, Arf6 works with RhoA, the main activator of ROCK1, to generate tumor-derived microvesicles, suggesting a potential role for the R-Ras family in this process." (PMID 34530870, 2021).
tumor (continued). "RhoA is known to be involved in cell migration and recruitment of LSECs and HSCs, which is a crucial event for the establishment and growth of experimental CRC tumours." (PMID 34885024, 2021). "Western blot analysis of tumor lysates shows that Rac1, Cdc42, or RhoA protein levels were not substantially decreased as a consequence of R-ketorolac treatment in vivo or after 5 days of treatment in cell culture." (PMID 33413202, 2021). "CircIARS negatively correlated with miR-122 and ZO-1 and positively correlated with RhoA and RhoA-GTP levels, increased F-actin expression and focal adhesion, thereby promoting tumor invasion and metastasis, which suggests the role of circIARS as a prognostic marker in PDAC." (PMID 33614648, 2021). "RhoA and YAP have been reported to promote the development of many tumor types, including OS." (PMID 34627383, 2021). "Data from TCGA studies support that RHOA is mainly deleted among all major cancer types, thus being a possible tumor suppressor such as PTEN and would not be a proper candidate for inhibitors." (PMID 34680293, 2021). "Significant results were not reported regarding the association of RhoA and ROCK expression with lymphatic metastasis and tumor size of BrCa, respectively." (PMID 33407452, 2021). "Furthermore, RhoA has been confirmed to be a downstream target of miR-326, which further activates the RhoA-ROCK signaling pathway and promotes tumor progression." (PMID 34885209, 2021). "These conferred advantages by RhoA likely explain the increase in incidence of metastatic lesions, though it did not affect tumour cell proliferation within them." (PMID 34241735, 2021). "Similarly, our data showed that lyso-PS can activate RhoA activity via GPR34/Gi axis, which proposes a potential new molecular mechanism of lyso-PS on tumor metastasis." (PMID 33875796, 2021). "Altogether, these results suggested that depriving RhoA/SF-regulated periFN matrices non-autonomously promotes fibroblast-mediated tumor cell growth." (PMID 33158289, 2020). "Treating the RhoA-CA-transfected MTF7 cells with cytochalasin D completely disrupted their SF actin filaments and periFN assembly, suggesting that SF actin cytoskeleton mediates the RhoA-activated periFN matrix assembly on adherent tumor cells." (PMID 33158289, 2020). "Given the role of RhoA in cell migration, we assessed the effect of RRAP on tumor metastasis." (PMID 33288739, 2020). "We found that the DEX-mediated increase of ROR1 levels correlated with the upregulation of RhoA GTPase, Hippo signaling effectors YAP/TAZ as well as BMI-1 expression, resulting in stemness phenotype and differentiation of OC tumor cells, including platinum-resistant samples." (PMID 32989221, 2020). "According to the idea that the same receptor might activate different signaling pathways in different tumor histotypes, in prostate cancer cells, LPA increases functional invadopodia formation through RhoA and NF-κB, controlling osteolytic metastases." (PMID 33178698, 2020). "Additionally, we show that the ROCK inhibitor RKI-1447 suppresses ROCK-dependent signaling, tumorigenicity, and invasion by affecting RHOA, RHOB, vimentin, and JUN in vitro and inhibits tumor growth in vivo." (PMID 31888022, 2019). "Here, we report that SHROOM2 not only participates in RhoA–ROCK-induced stress fiber formation and focal adhesion, but also had an unanticipated role in suppressing epithelial-to-mesenchymal transition (EMT) and tumor metastasis." (PMID 30683844, 2019). "Stable silencing of Plexin-B1 impaired Sema4D-mediated activation of the RhoA and SRPK1 signaling in tumor cells, and resulted in a reduction of microvessel density in xenografts generated in vivo, due to an unknown mechanism." (PMID 31052281, 2019).
tumor (continued). "3MC upregulated the epithelial–mesenchymal transition (EMT) and tumor biomarkers; the models exhibited the reciprocal expression of histone deacetylase 1 (HDAC1) and RhoA, namely increased HDAC1 and decreased RhoA expression, through hypoxia-inducible-factor (HIF)- and AhR-dependent mechanisms." (PMID 30872677, 2019). "Mechanistically upregulation of the RhoA-ROCK pathway in melanoma cancer cells stimulates the transcription and secretion of an entire cytokine transcriptional program that controls immune cell recruitment into the tumor environment." (PMID 31705019, 2019). "Tumors in the RHOA mutant groups were composed mainly of small tumor nests compared to those in the non-mutant groups." (PMID 31485674, 2019). "Although the effects of RhoA activation in the progression of various cancers are still contradictory, both the in vitro and in vivo results of our study demonstrated that 3MC-induced RhoA inhibition contributed to RCC-tumor-promoting effects." (PMID 30872677, 2019). "Although these recent advances in the field support a tumor suppressive role for RhoA, a comprehensive mechanistic analysis on altered RhoA expression in primary tumors and its subsequent effects on tumor microenvironment and metastasis is lacking." (PMID 31705019, 2019). "In that regard, RHOA IHC staining was significantly higher in tumor tissues than in adjacent normal tissues, in negative correlation with miR-31 expression." (PMID 31156701, 2019). "Finally, JMS-053 served as a critical tool compound in identifying RhoA functions as a distal signaling convergence point for PTP4A activity in both endothelial and tumor cells." (PMID 29492190, 2018). "In order to determine if targeting different components of the IGF-1/RhoA/ROCK crosstalk between BC cells and CAFs would affect primary tumor growth and metastasis, we treated MDA-MB-231 xenografts with the IGF-1R inhibitor PQ401, Y27632 or PQ401 combined with Y27632." (PMID 29535813, 2018). "Furthermore, we found that MKRN2 inhibited cell migration and invasion in NSCLC cells by regulating the expression of RhoA/ROCK1 and MMP9, thereby influencing the malignant behavior of tumor cells." (PMID 30103781, 2018). "In addition, the tumor suppressor RASSF1A prevents tumorigenesis via interacting with Smurf1 and promoting Smurf1-mediated ubiquitination of RhoA." (PMID 29080116, 2018). "Similar to our Y27632 findings, the knockout of either ROCK1 or ROCK2 in MDA-MB-231 cells did not affect tumor growth, whereas the intratumoral injection of anti-RhoA siRNA reduced tumor growth." (PMID 29535813, 2018). "Although Rho GTPases RhoA, RhoB, and RhoC share more than 85% amino acid sequence identity, they play very distinct roles in tumor progression." (PMID 29385717, 2018). "We next tested the impact of pharmacological intervention with PI3K/Akt or RhoA/ROCK signalling on p110αH1047R-induced centrosomal abnormalities, either before their genesis in primary cells or once they had been established in a tumour context." (PMID 29170395, 2017). "The finding of variable RHOA expression in diverse GC cell lines, is not surprising, considering the high degree of heterogeneity of this specific tumor type." (PMID 27806312, 2016). "Mechanistically, the ability of the TXA2-TP axis to regulate tumour development and metastasis can be explained by the ability of TPα/TPβ to regulate key mitogenic/ERK- and RhoA-mediated signalling cascades and, potentially, by its ability to regulate local inflammation and immunity." (PMID 27689401, 2016). "he RhoA/ROCK pathway participates in the process of angiogenesis in numerous types of cancer, by controlling the permeability, migration, proliferation, proliferation and morphogenesis of tumor cells." (PMID 26066055, 2015).
tumor (continued). "We confirmed these results via Western blotting analysis of tumor cells expressing AFAP1-AS1 siRNA, and found that RhoA, Rac2, Rab10, Rab11a, Rhogdi and Pfn1 were significantly upregulated, but RhoC, Rab11b and Lasp1 were significantly downregulated in NPC cell lines." (PMID 26246469, 2015). "In our study, there was a sharp increase of GGPPS1 in patients with vessel invasion and later tumor stage, suggesting that upregulated GGPPS1 could elevate prenylated RhoA, further accelerating invasion and intrahepatic metastasis." (PMID 24716791, 2014). "DLC1 (Deleted in Liver Cancer 1) gene encodes a RhoGTPase-activating protein (RhoGAP), which exerts most of its tumor suppressor functions through suppression of small Rho GTPases proteins RhoA, RhoB, RhoC and to some degree Cdc42, but not Rac." (PMID 24683532, 2014). "In group II, the RhoA-modulators CCG-1423, narciclasine, the pan-Rac inhibitor EHT-1864 as well as the adenylate-cyclase inhibitor KH7 mainly resulted in cytotoxic effects, which in turn are likely to impair tumor cell invasion." (PMID 24810913, 2014). "Expression of ROCK-I and -II proteins was decreased by exposure of tumor cells to HA-1077, while RhoA activity was not affected." (PMID 24908363, 2014). "The RhoA/Rho kinase (ROCK) pathway plays a crucial role in the process of angiogenesis in PCa, and studies have demonstrated that ROCK inhibitors decrease VEGF-induced angiogenesis and tumor cell growth." (PMID 25289078, 2014). "Unlike RhoA, RhoB is often down-regulated in human tumors and expression inversely correlates with tumor aggressiveness." (PMID 24279335, 2013). "Here, we demonstrate that p114RhoGEF, an activator of RhoA that associates with non-muscle myosin IIA, regulates collective cell migration of epithelial sheets and tumor cell invasion." (PMID 23185572, 2012). "Immunoblotting analysis revealed a higher RhoA expression in 69.2% (18/26) of HCC tumor tissues when compared with their adjacent non-tumorous tissues." (PMID 21347395, 2011). "Unlike RhoA and RhoC, the level of active-RhoB protein, which is a tumor suppressor gene, was up-regulated in both BxPC-3 and PanC-1 cells by BITC treatment." (PMID 22016776, 2011). "For this, Western blotting to detect phosphorylated and total levels of the Rac1 effectors p21 activated kinase (PAK-1/2), the RhoA effector Rho kinase (ROCK), and downstream signaling molecules AKT and ERK was done on the pooled tumor extracts from 11 mice per genotype." (PMID 20860838, 2010). "Unlike RhoA and RhoC, RhoB is often downregulated in human tumors and its expression inversely correlates with tumor aggressiveness." (PMID 20822528, 2010). "Over expression of RhoA has been observed in tumors from colon, breast and lung tissues, and was found to be significantly higher in grade III tumors than in grade I tumors in breast tissue, suggesting a link with tumor progression." (PMID 29147173, 2010). "Importantly, two clinical drugs, the RhoA inhibitor simvastatin and the YAP1/TEAD inhibitor verteporfin were determined to be the disruptors of this feed-forward signaling axis, inhibiting ICC tumor growth." (PMID 41513610, 2026). "In addition to discovering the crucial role of ANLN in cytokinesis via RhoA activation, we also illustrated that ANLN restrained the Hippo pathway by enhancing the activity of RhoA signaling, which together contributed to ANLN-mediated tumor-promoting effects on ICC." (PMID 41513610, 2026). "Overall, the available evidence suggests that μg, through the inhibition of adhesion and growth pathways (e.g., FAK, RhoA, YAP1, Cyclin D), cytoskeletal remodeling, and modulation of apoptosis/survival regulators, exerts a time- and cell type-dependent suppressive effect on tumor proliferation." (PMID 40940834, 2025).